CLDN12 (claudin 12)
Diseases named in the same sentence as CLDN12 in open-access papers:
CLDN12 is named in the same sentence as 46 diseases in open-access papers, as found by Europe PMC text mining. Sharing a sentence is not in itself a finding about the gene and the disease. The quoted sentences say what the papers report.
breast carcinoma (6 papers, 2016 to 2025). "For example, IL-1β promotes the proliferation, migration, angiogenesis, and release of HMGB1 in smooth muscle cells, while IL-18 promotes the migration of breast cancer cells by down-regulating claudin-12 and inducing the P38/MAPK pathway." (PMID 36233009, 2022). "Although IL-18/p38 MAPK pathway downregulates claudin-12 and promotes tumor invasion in breast cancer, indicating its possible anti-tumor effect, the upregulation of claudin-12 in colorectal cancer needs to be further studied." (PMID 31316506, 2019). "The results suggest that IL-18 is important for the induction of breast cancer cell migration by down-regulating claudin-12 and activating the p38 mitogen-activated protein kinase (MAPK) pathway [72•]." (PMID 27547510, 2016). "Upon knocking down these claudins, all except claudin-1 increased breast cancer cell migration with claudin-12 generating the most effects." (PMID 27547510, 2016). "As previously elaborated, CLDN12 exhibits distinct functions in the processes of proliferation and migration of various cancers, including osteosarcoma, pancreatic cancer, cervical cancer, breast cancer, and others." (PMID 41461671, 2025). "IL-18 plays an important role in inducing breast cancer cell migration by activating the p38 MAPK pathway and downregulating claudin-12." (PMID 38201482, 2023).
colorectal cancer (4 papers, 2019 to 2026). A primary or metastatic malignant neoplasm that affects the colon or rectum. "Based on analysis using TCGA database, CLDN12 mRNA is most abundantly overexpressed in colorectal cancer." (PMID 33917356, 2021). "CLDN12 is another DplUSE-containing gene, which is overexpressed in colorectal carcinomas." (PMID 41505098, 2026). "Furthermore, CLDN12 was expressed in colorectal cancer tissues." (PMID 33917356, 2021). "Our findings revealed that the mRNA expression levels of CLDN1, CLDN2, CLDN12, and CLDN14 were upregulated in colorectal cancer tissues relative to normal tissues in the Oncomine database, whereas CLDN3, CLDN5, CLDN7, CLDN8, CLDN11, CLDN15, and CLDN23 were downregulated, as previously reported." (PMID 35281827, 2022). "Moreover, in colorectal cancer and uterine cervical SCC tissues, CLDN12 was localized in the cytoplasm." (PMID 33917356, 2021). "In marked contrast, by immunohistochemistry, the anti-CLDN12 pAb did not detect any specific signal in normal liver tissues or colorectal cancer tissues." (PMID 33917356, 2021). "In the current study, however, we showed by immunohistochemistry that the anti-CLDN12 pAb, unlike the anti-CLDN12 mAb, detected no specific signal in normal liver or colorectal cancer FFPE tissues." (PMID 33917356, 2021).
glioma (3 papers, 2025 to 2026). A benign or malignant brain and spinal cord tumor that arises from glial cells (astrocytes, oligodendrocytes, ependymal cells). "A high expression of CLDN12 was found to be associated with a poor prognosis in patients with LUAD, cervical squamous cell carcinoma and endocervical adenocarcinoma (CESC), KICH and lower-grade glioma (LGG)." (PMID 41461671, 2025). "Given the crucial roles of CLDN12 and CLDN15 in maintaining tight junctions and barrier function, their CNV‐driven expression changes might significantly impact glioma progression through altered cell–cell adhesion and blood–brain barrier integrity." (PMID 41425851, 2025).
Hypercalciuria (3 papers, 2020 to 2025). "This has also been observed in claudin-2 and claudin-12 double-KO mice, despite more severe hypercalciuria, and raises the intriguing question of whether claudin-2 in the PT is needed in some way for 1-hydroxylation of 25-hydroxyvitamin D." (PMID 41066193, 2025). "Cldn2 KO but not Cldn12 KO mice have hypercalciuria, although direct measurement of perfused proximal tubules from Cldn12 KO mice confirm reduced Ca2+ permeability." (PMID 34810264, 2021). "Cldn2 KO mice exhibit hypercalciuria and increased net intestinal Ca2+ absorption, while Cldn12 KO mice do not have an overt Ca2+ phenotype." (PMID 34810264, 2021). "Why claudin-2 KO mice demonstrate hypercalciuria and claudin-12 null mice do not is unclear, but is perhaps due to a greater abundance of claudin-2 in the proximal tubule." (PMID 32197346, 2020). "It is surprising then that claudin-12 null mice did not display hypercalciuria in response to a failure to reabsorb Ca2+ from the proximal straight tubule." (PMID 32197346, 2020). "However, the deletion of Cldn12 does not induce hypercalciuria or an increase in calciotropic hormone levels." (PMID 32197346, 2020).
lung squamous cell carcinoma (3 papers, 2021 to 2025). "Claudin-12 (CLDN12) has been shown to be expressed in lung squamous cell cancer and osteosarcoma." (PMID 38540693, 2024). "In addition, the same researchers found upregulated expression of claudin-12 in lung squamous cell carcinoma (SqCC) tissues, suggesting the CLDN12 gene as a proto-oncogene in SqCC." (PMID 33922921, 2021).
osteosarcoma (3 papers, 2021 to 2025). A usually aggressive malignant bone-forming mesenchymal neoplasm, predominantly affecting adolescents and young adults. "CLDN12 has been shown to facilitate the proliferation and migration of osteosarcoma cells via the PI3K/AKT signaling pathway." (PMID 41461671, 2025).
cervical cancer (2 papers, 2021 to 2025). A primary or metastatic malignant neoplasm involving the cervix. "By semiquantification of the CLDN12 expression in cervical cancer tissues, 26 of the 138 cases (18.8%) showed low CLDN12 expression, and the remaining 112 cases (81.2%) exhibited high CLN12 expression." (PMID 33917356, 2021). "We demonstrated in the current study that reduced CLDN12 expression predicts poor outcome in patients with cervical cancer." (PMID 33917356, 2021). "Analysis of a larger number of cases would be required to obtain more solid conclusions about the clinicopathological relevance of the low CLDN12 expression in patients with cervical cancer." (PMID 33917356, 2021). "We also demonstrated that the reduced CLDN12 expression was an independent prognostic variable for cervical cancer." (PMID 33917356, 2021). "We also demonstrated, via univariable and multivariable analyses, that the low CLDN12 expression represents a significant prognostic factor for the DSS of cervical cancer patients (HR 3.412, p = 0.002 and HR 2.615, p = 0.029, respectively)." (PMID 33917356, 2021). "By performing immunohistochemical staining and semiquantification, we evaluated the relationship between CLDN12 expression and clinicopathological parameters in tissues from 138 cases of cervical cancer." (PMID 33917356, 2021). "Using this specific mAb, we show that the diminished CLDN12 expression is a poor prognostic biomarker for cervical cancer." (PMID 33917356, 2021). "It is unknown how the low CLDN12 expression contributes to poor prognosis in cervical cancer subjects." (PMID 33917356, 2021). "Along this line, the diminished CLDN12 expression may stimulate certain intracellular signaling pathways, such as YAP, resulting in cervical cancer progression." (PMID 33917356, 2021). "Among the analyzed variables, the low CLDN12 expression (HR 2.615, p = 0.029), FIGO stage IIb/III/IV (HR 4.075, p = 0.002), and recurrence (HR 14.852, p < 0.001) were independent prognostic factors for the DSS of cervical cancer patients." (PMID 33917356, 2021).
lung carcinoma (2 papers, 2021 to 2024). "Previous studies revealed that miR-146a-5p promotes lung cancer cell proliferation by targeting claudin-12, and overexpression of miR-146 or knockout of its target gene, notch 1, inhibits mouse neural stem cell proliferation in serum-free medium." (PMID 33531066, 2021).
pancreatic cancer (2 papers, 2023 to 2025). "Additionally, CLDN12 is thought to drive the EMT process of pancreatic cancer cells." (PMID 41461671, 2025).
acute myeloid leukemia (1 paper, 2025). Acute myeloid leukemia (AML) is a group of neoplasms arising from precursor cells committed to the myeloid cell-line differentiation. "Conversely, in patients with KIRC and acute myeloid leukemia (LAML), a high CLDN12 expression was linked to a better prognosis (P < 0.05)." (PMID 41461671, 2025).
breast invasive carcinoma (1 paper, 2025). "Immunohistochemistry (IHC) of tumor samples and normal tissues from the Human Protein Atlas (HPA) database revealed that CLDN12 protein was highly expressed in LUSC, PRAD, COAD, READ, LIHC, cholangiocarcinoma (CHOL), breast invasive carcinoma (BRCA), and BLCA tumor tissues." (PMID 41461671, 2025).
colitis (1 paper, 2021). Inflammation of the colon. "Claudin 8 and claudin 12 had decreased expression in colitis, consistent with the literature, and TGS 121 treatment had no influence." (PMID 33803793, 2021).
colon adenocarcinoma (1 paper, 2025). "CLDN12 is expressed in human colon adenocarcinoma (COAD) LS180 cells and exerts a pivotal influence on the dissemination of cancer cells." (PMID 41461671, 2025).
dermatitis (1 paper, 2009). An inflammatory process affecting the skin. "While the distribution of Cldn6, Cldn11, Cldn12 and Cldn18 corresponded to the expanded suprabasal compartment of the dermatitis-affected Inv-Cldn6-CΔ196 epidermis, immunostaining was less intense and membranous localization less evident in lower suprabasal layers." (PMID 19915705, 2009).
fibrosarcoma (1 paper, 2025). A malignant mesenchymal fibroblastic neoplasm affecting the soft tissue and bone. "A study of transplanted tumors (fibrosarcoma, melanoma, and Lewis lung cancer) in Cldn12-deficient mice showed that homotypic interactions between CLDN12 contribute to the migration of myeloid-derived suppressor cells (MDSCS)." (PMID 41461671, 2025).
glioblastoma multiforme (1 paper, 2025). "Next, we plotted the ROC with AUC greater than 0.8 for CLDN12 in pan-cancer and found that it was largest in glioblastoma multiforme (GBM) at 0.9621, followed by LUAD at 0.9311." (PMID 41461671, 2025).
Hyperammonemia (1 paper, 2012). An increased concentration of ammonia in the blood. "In an immortalized murine cell culture model, only claudin-12 mRNA levels were down-regulated under conditions mimicking hyperammonemia." (PMID 22373538, 2012).
multiple sclerosis (1 paper, 2019). A progressive autoimmune disorder affecting the central nervous system resulting in demyelination. "Nonetheless, our study rules out an essential role for claudin-12 in regulating BBB integrity under non-inflammatory or neuroinflammatory conditions, as we did not observe any aggravation of experimental autoimmune encephalomyelitis (EAE), an animal model of multiple sclerosis (MS)." (PMID 31511021, 2019).
pancreatic adenocarcinoma (1 paper, 2023). "CLDN12 is a member of the claudins family that is involved in cell-cell interaction, and its high-level expression facilitates the malignant phenotypes of pancreatic adenocarcinoma cells." (PMID 37924077, 2023). "Furthermore, it has been illustrated that miR-150 target CLDN12 mRNA, a transmembrane protein, and reduce pancreatic adenocarcinoma cell migration." (PMID 37924077, 2023).
tongue SCC (1 paper, 2021). "Although we do not know why CLDN12 possesses distinct subcellular localization it has been reported that the CLDN1 localization is altered from cell membranes to cytoplasm at the invasion front of tongue SCC tissues." (PMID 33917356, 2021).
cancer (9 papers, 2020 to 2026). A tumor composed of atypical neoplastic, often pleomorphic cells that invade other tissues. "Conversely, CLDN1 and CLDN12, which are associated with cancer invasion and progression, were significantly reduced by all three antibiotics 17,22,24." (PMID 40847193, 2025). "Altogether, it indicates that the expression of CLDN5, CLDN11, CLDN2, CLDN7, and CLDN12 is associated with regulating the key cancer-associated pathways in the COAD and GSEA datasets." (PMID 37799140, 2023). "Besides, the expression levels of CLDN2, CLDN7, and CLDN12 are negatively correlated with some of the cancer-associated pathways." (PMID 37799140, 2023). "Iravani and co-workers showed that expression of claudin-12 is upregulated in estrogen receptor (ER)-negative breast cancer and its expression is associated with poor prognosis, indicating that claudin-12 may serve as a marker for predicting the survival in this cancer subtype." (PMID 32197343, 2020). "Aside from its low expression in CHOL, KICH, KIRC, and SARC, CLDN12 exhibits high expression in most other cancer types." (PMID 41461671, 2025). "The integration of 33 types of cancer in GTEx and TCGA databases showed that CLDN12 expression was significantly different in most cancers compared with normal tissues (P < 0.05)." (PMID 41461671, 2025). "In subsequent studies, we will further elaborate on the mechanism of action of CLDN12 and its potential value in pan-cancer research through both in vivo and in vitro experiments." (PMID 41461671, 2025). "Another issue that should be discussed is the subcellular localization of the CLDN12 protein in the normal and cancer tissues analyzed." (PMID 33917356, 2021). "Our findings identified the essential role of claudin-12 in the migration of cancer cells through claudin-12 expressing tissues in the process of metastasis." (PMID 33922921, 2021). "On the other hand, upon searching the Cancer Genome Atlas (TCGA) database, CLDN12 mRNA is highly overexpressed in diverse histological types of human cancer tissues, such as SCC and ADCA in a range of organs." (PMID 33917356, 2021). "In-depth exploration of CLDN12 may thus yield valuable insights to advance cancer research in a broader context and ultimately benefit a larger population of cancer patients." (PMID 41461671, 2025). "The novel anti-CLDN12 mAb could be a valuable tool to evaluate the biological relevance of the CLDN12 expression in diverse cancer types and other diseases." (PMID 33917356, 2021). "Anti-claudin-12 antibodies and competitive inhibitory peptides could be useful in the therapeutic approach applied to cancer metastasis in tissues expressing claudin-12." (PMID 33922921, 2021). "Interestingly, CLDN12 is highly expressed in most types of cancer." (PMID 41461671, 2025). "Most notably, many of these early response alterations in the cancer cells are known pro‐angiogenic transcripts, including ITGA2, CLDN12, SMAD7, MET, KLF4, ID3 and ID1." (PMID 40116596, 2025). "We hypothesized that cancer cells use claudin-12 to migrate through the tight junctions during metastasis and that blocking this protein or the competitive binding of cancer cells to peptides derived from the extracellular part of claudin-12 will reduce the metastatic process." (PMID 33922921, 2021). "The novel anti-CLDN12 mAb would be extremely valuable to determine the biological relevance of the CDLN12 expression in diverse diseases, including various types of cancer." (PMID 33917356, 2021). "We found that epithelial-derived cancer cell lines from the colon (LS180, Caco-2, HT-29) and the lung (A549) express claudin-12, while liver endothelial SK-Hep-1 and cervix epithelial HeLa cancer cells were claudin-12 negative." (PMID 33922921, 2021).
cancer (continued). "We selected six DplUSE-containing genes (KIF20A, EXT2, CLDN12, MBNL2, MED18, DKC1) from the 31 orthologous genes identified by the bioinformatic script that are common to human, mouse, and zebrafish and that have a relevant physiological function in malignant neoplasms." (PMID 41505098, 2026).
tumor (7 papers, 2016 to 2026). "In the study of mouse skin tumors, the amount of CLDN12 in the suprabasal cortex decreases with tumorigenesis and tumor progression." (PMID 41461671, 2025). "CLDN12 is upregulated in LUAD and is associated with the tumor stage and lymph nodes metastasis of LUAD patients." (PMID 41461671, 2025). "Significant differences in CLDN3, CLDN4, CLDN5, CLDN6, CLDN9, CLDN11, and CLDN12 expression were evident as a function of tumor stage." (PMID 35281827, 2022). "Notably, CLDN12 displayed differential expression patterns across most tumor entities, with particularly pronounced upregulation in LUAD (log2FC = 1.2)." (PMID 41461671, 2025). "Thus, claudin-12 is a suitable biomarker for tumor progression and metastasis and an attractive target for antitumor therapy." (PMID 33922921, 2021). "Therefore, blocking expression of claudin-12 with anti-claudin-12 antibodies should have a beneficial effect, inhibiting tumor progression and metastasis in tissues expressing claudin-12." (PMID 33922921, 2021). "Therefore, as a transmembrane protein, CLDN12 may modulate the metastatic ability of tumor cells through regulating calcium influx, or by interacting with cadherins and influencing calcium-dependent signal transduction pathways." (PMID 41461671, 2025). "CLDN12 is up-regulated in LUAD, and its expression is correlated with the tumor stage and lymph nodes metastasis in LUAD patients." (PMID 41461671, 2025). "Specifically, CLDN12 was significantly upregulated in LUAD, correlating with advanced tumor stage, lymph nodes metastasis, and poor survival outcomes." (PMID 41461671, 2025). "Previous studies exploring the effects of CLDN1, CLDN2, CLDN4, CLDN11, CLDN12, CLDN14, and CLDN23 expression on CRC tumor growth have yielded findings consistent with our results in the present study." (PMID 35281827, 2022). "Moreover, we analyzed the functions and potential pathways of crucial genes related to CLDN12 expression, including HSPA8 and HIF-1α, in the process of tumor progression." (PMID 41461671, 2025).
infection (2 papers, 2021 to 2026). The state of being infected such as from the introduction of a foreign agent such as serum, vaccine, antigenic substance or organism. "Viral entry is a key step in establishing infection, where the host factor CLDN12 promotes HCV invasion." (PMID 42312836, 2026).
psychiatric disease (1 paper, 2020). "Correlation analysis revealed that there was a consistent and robust negative correlation between the expression of tight junction mRNAs and the duration of psychiatric disease with longer duration of disease associated with reduced expression of CLDN12 and TJP1 notably." (PMID 33139732, 2020). "We also show that levels of tight junction mRNA transcripts, including claudin-5, claudin-12 and ZO-1 correlate with disease duration and age of onset of a range of psychiatric disorders." (PMID 33139732, 2020).
CLDN12 also shares sentences with these, for which no sentence is quoted: schizophrenia (3 papers); colon cancer (2); hepatocellular carcinoma (2); Anxiety (1); asthma (1); bipolar disorder (1); bladder urothelial carcinoma (1); cervical squamous cell carcinoma (1); cholangiocarcinoma (1); depression (1); endocervical adenocarcinoma (1); esophageal carcinoma (1); gastric cancer (1); head-neck squamous cell carcinoma (1); Hypocalcemia (1); lymph node metastasis (1); melanoma (1); Obesity (1); ovarian carcinoma (1); prostate adenocarcinoma (1); rectal adenocarcinoma (1); stomach adenocarcinoma (1).